DEAF1 (DEAF1 transcription factor)
Description:
Transcription factor that binds to sequence with multiple copies of 5'-TTC[CG]G-3' present in its own promoter and that of the HNRPA2B1 gene. Down-regulates transcription of these genes. Binds to the retinoic acid response element (RARE) 5'-AGGGTTCACCGAAAGTTCA-3'. Activates the proenkephalin gene independently of promoter binding, probably through protein-protein interaction. When secreted, behaves as an inhibitor of cell proliferation, by arresting cells in the G0 or G1 phase. Required for neural tube closure and skeletal patterning. Regulates epithelial cell proliferation and side-branching in the mammary gland. Controls the expression of peripheral tissue antigens in pancreatic lymph nodes. Isoform 1 displays greater transcriptional activity than isoform 4. Isoform 4 may inhibit transcriptional activity of isoform 1 by interacting with isoform 1 and retaining it in the cytoplasm. Transcriptional activator of EIF4G3.
Synonyms: NUDR; SPN; ZMYND5; MRD24; NEDHELS; VSVS
Tractability: Small molecule: a structure with a bound ligand is known. Antibody: UniProt places it where antibodies can reach, with medium confidence; its Gene Ontology location is reachable by antibodies, with medium confidence. PROTAC: ubiquitination databases record sites on it.
Gene: Protein-coding gene on chromosome 11 (644,224 to 707,118, reverse strand). Ensembl gene ENSG00000177030.
Subcellular location: Nucleus (Isoform 1); Cytoplasm; Secreted (Isoform 2); Secreted (Isoform 3); Cytoplasm (Isoform 4); Nucleus
Subcellular location (Human Protein Atlas): Nucleoli fibrillar center; Nucleoplasm
Gene Ontology:
Molecular function: DNA-binding transcription repressor activity, RNA polymerase II-specific; protein binding; RNA polymerase II transcription regulatory region sequence-specific DNA binding; DNA-binding transcription factor activity, RNA polymerase II-specific; DNA binding
Biological process: negative regulation of DNA-templated transcription; negative regulation of transcription by RNA polymerase II; positive regulation of DNA-templated transcription; regulation of mammary gland epithelial cell proliferation; anatomical structure morphogenesis; embryonic skeletal system development; germ cell development; neural tube closure; regulation of transcription by RNA polymerase II; transcription by RNA polymerase II; behavioral fear response; visual learning
Cellular component: fibrillar center; nucleoplasm; chromatin; nucleus; cytoplasm; extracellular region; RNA polymerase II transcription regulator complex
Genetic constraint (gnomAD): Loss-of-function variants: 56 observed, 59.31 expected, observed/expected ratio (o/e) 0.94, 90% interval 0.76 to 1.18. The upper end of that interval is the gene's LOEUF score, 1.18, which puts it in group 5 of 6, group 1 being the genes least tolerant of losing a copy. Missense variants: 685 observed, 747.16 expected, observed/expected ratio (o/e) 0.92, 90% interval 0.86 to 0.98. Synonymous variants: 385 observed, 325.4 expected, observed/expected ratio (o/e) 1.18, 90% interval 1.09 to 1.29.
Homologues: Orthologues: macaque DEAF1 (99% identical), rat Deaf1 (94% identical), mouse Deaf1 (94% identical), guinea pig DEAF1 (93% identical), pig DEAF1 (93% identical), chimpanzee DEAF1 (90% identical), dog DEAF1 (88% identical), tropical clawed frog deaf1 (56% identical), zebrafish deaf1 (53% identical), Drosophila melanogaster Deaf1 (27% identical).
Diseases named in the same sentence as DEAF1 in open-access papers:
DEAF1 is named in the same sentence as 30 diseases in open-access papers, as found by Europe PMC text mining. Sharing a sentence is not in itself a finding about the gene and the disease. The quoted sentences say what the papers report.
Anxiety (10 papers, 2014 to 2025). Intense feelings of nervousness, tension, or panic often arise in response to interpersonal stresses. "DEAF1 has also been implicated in major depression, anxiety, suicidal tendencies, and panic disorder though one of its target genes, 5-HT1A38." (PMID 26743651, 2016). "Our results in the mixed C57BL6-Balb/c background suggest that altered signaling of 5-HT1A receptors could be one mechanism of adaptation of the anxiety phenotype to the loss of Deaf1 across generations." (PMID 27488351, 2016). "The rs6295 polymorphism in the HTR1A promoter affects 5-HT1A expression via the transcription factor Deaf-1, altering serotonergic activity and contributing to anxiety and depression mechanisms." (PMID 41373485, 2025). "Conditional knockout of Deaf1 gene in mouse model leads to a phenotype with impaired memory and increased anxiety." (PMID 31477183, 2019). "Deaf1 binds the HTR1A promoter in an allele-specific manner, with the non-binding G(-1019) allele associated with major depression, anxiety and resistance to antidepressant and atypical antipsychotic treatment." (PMID 29636529, 2018). "In Deaf1 knockout mice, loss of Deaf1 led to a functional increase in 5-HT1A autoreceptors and an anxiety phenotype in males and females." (PMID 29636529, 2018). "The reduced anxiety in females differs from the anxiety phenotype seen upon loss of HTR1A repressors Freud-1 and Deaf1." (PMID 29636529, 2018). "The female Deaf1-/- mice displayed a mixed phenotype, mildly anxious in the elevated plus maze, but with apparently reduced anxiety in the light-dark test." (PMID 27488351, 2016). "Male Deaf1 knockout mice displayed anxiety-like behavior in the open field and light-dark tests, while female Deaf1-/- mice showed increased anxiety only in the elevated plus maze." (PMID 27488351, 2016). "Taken together, the anxiety-like behavior in Deaf1-/- mice was sex-dependent: the most prominent anxiety phenotype occurred in light-dark test for males, while in the EPM for female Deaf1-/- mice." (PMID 27488351, 2016). "The anxiety phenotype in Deaf1-/- males is consistent with the role in males of reduced 5-HT1A autoreceptor function during the early post-natal period in the anxiety phenotype, that remains to be addressed in females." (PMID 27488351, 2016). "Consistent with altered 5-HT1A autoreceptor function in male Deaf1-/- mice, anxiety-like behaviors differed in male and female Deaf1-/- mice." (PMID 27488351, 2016). "In order to address the effects of Deaf1 gene deletion on behavior, we performed pilot experiments testing locomotor activity, anxiety, and depression phenotypes in late generation mice and observed differences between males and females." (PMID 27488351, 2016). "Male Deaf1-/- mice demonstrated greater anxiety-like behavior in two tests (light-dark and open field), but not in the elevated plus maze test." (PMID 27488351, 2016). "The G-1019 allele may inhibit the Deaf-1-mediated transcription of 5-HT1A and lessen the release of 5-HT, thereby amplifying anxiety symptoms that have a lasting impact on the lives of the patients." (PMID 39207450, 2024). "Loss of Deaf1 resulted in a mild anxiety phenotype that was sex-and test-dependent, with no change in depression-like behavior." (PMID 27488351, 2016). "Overall, two of three tests indicated that male Deaf1-/- mice tend to have higher anxiety." (PMID 27488351, 2016). "In the light-dark test, male Deaf1-/- mice showed reduced time in the light and had significantly increased latency to enter the dark chamber, indicating a freezing response when initially placed in the light, both consistent with an anxiety phenotype." (PMID 27488351, 2016). "In contrast, Deaf1-/- females displayed apparently reduced anxiety in the light-dark test, reduced latency to enter the dark chamber suggesting that they are less sensitive to light than the males in this test, which has the brightest light intensity of the tests." (PMID 27488351, 2016).
Anxiety (continued). "Importantly, the anxiety phenotype of our mixed background Deaf1 null mice is consistent with the brain-specific knockout of Deaf1, which in male mice induced an anxiety phenotype in one test, and no depression-like effects." (PMID 27488351, 2016). "Knockout of Deaf1 led to a sex-dependent effect with an initial increase in hypothermia response and anxiety in males that declined additional generations, while females had normal autoreceptor function and a partial anxiety effect." (PMID 27488351, 2016). "Although activation of Deaf1 could be beneficial in treatment of anxiety and depression, Deaf1 may also have beneficial actions on the immune system including enhancing responses to peripheral tissue antigens and to viral antigens." (PMID 24936175, 2014). "Indeed, several mRNAs that were differentially expressed in stressed visual cortices are recognized mediators of brain development and neurodevelopmental disorders, including Deaf1 in memory deficits and anxiety-like behaviours, Faim2 in obsessive compulsive disorder and Hrh3 in schizophrenia." (PMID 39739746, 2024). "Hence, the weak anxiety phenotype in females may reflect reduced exploration, while the greater latency of the Deaf1-/- males to escape to the dark side in the light-dark test could be interpreted as a light-dependent panic response." (PMID 27488351, 2016). "For example, knockout of the HTR1A repressor Deaf1 results in increased 5-HT1A autoreceptor expression but greater functional uncoupling in females, and a sex- and test-dependent anxiety phenotype." (PMID 31114473, 2019). "Deaf1 −/− females showed increased anxiety in the EPM and OF, but reduced anxiety in the light-dark test, while males showed increased anxiety in the light-dark test." (PMID 29636529, 2018). "Female Deaf1-/- mice showed a 75 % reduction in time in open arms in the EPM compared to wild-type mice, suggesting an anxiety phenotype in this test." (PMID 27488351, 2016). "In summary, our data indicate that Deaf1 regulates 5-HT1A autoreceptors in vivo and show that upon loss of Deaf1 regulation, compensatory changes occur over generations leading to adaptation of receptor responsiveness that may underlie the mild anxiety phenotype." (PMID 27488351, 2016). "This is consistent with previous findings in brain-specific male Deaf1 knockout C57BL6 mice, which showed a mild anxiety phenotype in this test with no change in open arm time." (PMID 27488351, 2016).
depression (9 papers, 2011 to 2025). "The 5-HT1A C(-1019)G polymorphism (rs6295) appears to alter 5-HT1A receptor expression in humans and is associated with major depression, suggesting a role for Deaf1 in human depression." (PMID 24936175, 2014). "DEAF-1 is an important transcriptional regulator that is required for embryonic development and linked to clinical depression and suicidal behavior in humans." (PMID 23372760, 2013). "DEAF-1 is an important transcriptional regulator that is required for embryonic development and is linked to clinical depression and suicidal behavior in humans." (PMID 23372760, 2013). "Deaf1 has been implicated in the regulation of 5-HT1A receptor expression in vitro, and indirectly in major depression in humans." (PMID 27488351, 2016). "The sex dependence of Deaf1 function in mice is consistent with a greater role for 5-HT1A autoreceptors in sensitivity to depression in men." (PMID 27488351, 2016). "The expression of Deaf1, Freud-1 and Freud-2 also appears to be dys-regulated in human depression in a region-specific manner." (PMID 21619616, 2011). "Alternately, pharmacological modification of transcription factors that show regions specific activity on 5-HT1A transcription, such as Deaf1 or MR, may provide new approaches to treat depression or augment antidepressant activity." (PMID 24936175, 2014). "Therefore, hypermethylation of DEAF1 could potentially reduce its availability to repress 5-HT1A autoreceptor expression, which in turn is linked to depression." (PMID 31178771, 2019). "In antidepressant-free female depressed subjects Deaf1 and 5-HT1A protein levels were decreased, consistent with reduced 5-HT1A-mediated inhibition of pyramidal neurons in depression that may be driven by reduced Deaf1 expression." (PMID 24936175, 2014). "We identify a set of conserved transcription factors including Deaf1, Freud-1/CC2D1A, Freud-2/CC2D1B and glucocorticoid receptors that may confer deleterious regional changes in 5-HT1A receptors in depression, and how future treatments could target these mechanisms." (PMID 24936175, 2014). "However, in the human HTR1A promoter, Deaf1 fails to bind to its site at the rs6295 G-allele, leading to increased 5-HT1A autoreceptor expression to reduce serotonergic activity and predispose to depression." (PMID 27488351, 2016).
Intellectual disability (6 papers, 2016 to 2023). "De novo heterozygous mutations in DEAF1 cause intellectual disability, speech impairment, and autistic behaviors." (PMID 38025430, 2023). "Protein interactions of DEAF1-DEAF-1 and DEAF1-Ku70 are mediated by the SAND domain of the protein DEAF-1, and specific mutations in the domain result in moderate to severe asyndromic intellectual disability in humans." (PMID 36520265, 2022). "For example, increased levels of alpha defensins (encoded by DEFA1) have been reported in the CSF of patients with AD, whereas mutations in DEAF1 gene can cause severe intellectual disability and behavioral problems." (PMID 31477183, 2019). "Retinoic acid is crucial for early development of the central neural system, and DEAF1 is associated with intellectual disability." (PMID 26743651, 2016). "DEAF1 (DEAF1 transcription factor): Mental retardation, autosomal dominant 24 (intellectual disability and impairments in adaptive behavior)." (PMID 31031802, 2019).
autism (5 papers, 2023 to 2025). Persistent deficits in social interaction and communication and interaction as well as a markedly restricted repertoire of activity and interest as well as repetitive patterns of behavior. "The autism risk genes involved in transcriptional regulation (DEAF1) and the cytoskeleton (DPYSL2) were strongly expressed at the end of the lineage." (PMID 39363111, 2024). "A family-based study in a consanguineous Omani family using WES reported a homozygous variant in DEAF1 in three affected siblings with autism and ID." (PMID 38572415, 2024). "Additionally, homozygous recessive mutations in DEAF1 have been identified in subjects with autism, hypotonia, language delay, ID, basal ganglia dysfunction, and epilepsy." (PMID 38025430, 2023).
breast carcinoma (5 papers, 2008 to 2022). "For example Rac3 GTPase, which is linked to breast cancer, cellular migration and adhesion, is transcriptionally upregulated by DEAF1 in immortalised mammary epithelial cells." (PMID 22723967, 2012). "Together these results support the idea that high levels of LMO4 in the nucleus, which is a hallmark of sporadic breast cancers, may upset the delicate balance between interactions with partner proteins such as DEAF1." (PMID 22723967, 2012). "In vitro and in vivo overexpression of DEAF-1 was found to promote proliferation of mammary epithelium; its role in breast cancer occurrence suggests of its activity as an oncoprotein." (PMID 36520265, 2022). "Manipulating the interaction between LMO4 and DEAF1 to prevent the formation of aberrant transcriptional complexes may represent a potential novel therapeutic strategy with which to combat breast cancer." (PMID 22723967, 2012). "Intriguingly, these functions may parallel the proliferative, migratory and invasive functions ascribed to LMO4, a partner of DEAF-1, in human breast cancer cell lines." (PMID 18826651, 2008). "DEAF-1 is a binding partner of LMO4 playing an important role in development of mammary gland and genesis of breast cancers." (PMID 36520265, 2022). "DEAF-1 has also been known to interact through LMO4 with the tumor suppressor BRCA1, potentially linking it to suppression of breast cancer development." (PMID 36520265, 2022). "Through LMO4, DEAF-1 also interacts with the tumor suppressor BRCA1, potentially linking DEAF-1 to breast cancer development." (PMID 23372760, 2013). "DEAF-1 has also been identified as a protein partner of LMO4 that plays important roles in mammary gland development and breast cancers." (PMID 23372760, 2013). "The transcription factor DEAF-1 has been identified as a high affinity binding partner of the LIM-only protein LMO4 that plays important roles in mammary gland development and breast cancer." (PMID 18826651, 2008). "Given the potential functional significance of this interaction in breast cancer, we sought to understand how LMO4 and DEAF1 might cooperate to regulate cell proliferation." (PMID 22723967, 2012). "The transcriptional co-regulator LMO4 (LIM-only protein 4) and the transcription factor DEAF1 (Deformed epidermal autoregulatory factor 1/NUDR/Suppressin) have several properties that suggest they act in common to regulate normal development and breast cancer." (PMID 22723967, 2012). "Although Lmo4 transgenic mice develop hyperplasia and mammary intraepithelial neoplasia or adenosquamous carcinoma, overexpression of Deaf-1 did not lead to mammary tumors." (PMID 18826651, 2008). "Although proliferation was enhanced in Deaf-1 transgenic mice, overexpression of this gene was not sufficient to induce the formation of mammary tumors." (PMID 18826651, 2008). "We therefore conclude that overexpression of Deaf-1 is not sufficient to induce mammary tumors." (PMID 18826651, 2008).
epilepsy (4 papers, 2017 to 2025). A brain disorder characterized by episodes of abnormally increased neuronal discharge resulting in transient episodes of sensory or motor neurological dysfunction, or psychic dysfunction. "Out of the 14 patients carrying 22q13 deletions and having seizures, 4 were carrying an additional CNV covering a known risk gene for epilepsy: KCNT1 (OMIM: 608167), MYT1L (OMIM: 613084), DEAF1 (OMIM: 602635) and SLC25A22 (OMIM: 609302)." (PMID 29263841, 2017).
schizophrenia (3 papers, 2018 to 2025). A major psychotic disorder characterized by abnormalities in the perception or expression of reality. "DNA methylation of the Deaf1 site is associated with negative symptoms of schizophrenia and correlates with antipsychotic resistance." (PMID 29636529, 2018).
neuroblastoma (2 papers, 2018 to 2023). Neuroblastoma (NB) is the most common solid, extracranial childhood tumor. "In 5-HT1A promoter-reporter assays, human HEK293 kidney and 5-HT1A-expressing SKN-SH neuroblastoma cells, transfection of Deaf1 reduced 5-HT1A promoter activity by ~45%." (PMID 37958600, 2023). "Our findings are consistent with Deaf1 repressor activity at the 5-HT1A promoter in HEK-293 and SKN-SH neuroblastoma cells." (PMID 37958600, 2023).
type 1 diabetes (2 papers, 2019). "DEAF1 regulates the transcription of multiple genes and has been implicated in type 1 diabetes, cancer, and IFNβ production." (PMID 31178771, 2019).
acute GVHD (1 paper, 2020). "Deaf1 gene expression was reduced early in FRCs following acute GVHD onset and this change was coincidental with reduced PTA gene expression." (PMID 31917684, 2020). "Future studies involving FRC-specific deletion of Deaf1 will provide further insight as to whether its downregulation in acute GVHD is solely responsible for reduced PTA expression." (PMID 31917684, 2020).